RNU6-906P (RNA, U6 small nuclear 906, pseudogene)
Gene: Small nuclear RNA gene on chromosome 6 (146,639,700 to 146,639,769, forward strand). Ensembl gene ENSG00000207431.
Homologues: Orthologues: chimpanzee U6 (100% identical), macaque U6 (97% identical), dog U6 (89% identical), dog U6 (86% identical), pig U6 (86% identical). Paralogues in human: RNU6-944P (94% identical), RNU6-116P (93% identical), RNU6-310P (93% identical), RNU6-698P (93% identical), RNU6-1050P (91% identical), RNU6-1060P (91% identical), RNU6-1243P (91% identical), RNU6-15P (91% identical), RNU6-20P (91% identical), RNU6-21P (91% identical), RNU6-24P (91% identical), RNU6-33P (91% identical), and 1286 more.